GGA2 (golgi associated, gamma adaptin ear containing, ARF binding protein 2)
Description:
Plays a role in protein sorting and trafficking between the trans-Golgi network (TGN) and endosomes. Mediates the ARF-dependent recruitment of clathrin to the TGN and binds ubiquitinated proteins and membrane cargo molecules with a cytosolic acidic cluster-dileucine (DXXLL) motif. Mediates export of the GPCR receptor ADRA2B to the cell surface. Regulates retrograde transport of phosphorylated form of BACE1 from endosomes to the trans-Golgi network.
Synonyms: Vear; KIAA1080
Tractability: Antibody: UniProt places it where antibodies can reach, with high confidence. PROTAC: UniProt records ubiquitination sites on it; ubiquitination databases record sites on it; its protein half-life has been measured.
Gene: Protein-coding gene on chromosome 16 (23,462,213 to 23,521,995, reverse strand). Ensembl gene ENSG00000103365.
Subcellular location: Golgi apparatus, trans-Golgi network membrane; Endosome membrane; Early endosome membrane
Subcellular location (Human Protein Atlas): Golgi apparatus
Pathways (Reactome):
Metabolism of proteins: Amyloid fiber formation
Vesicle-mediated transport: TBC/RABGAPs
Gene Ontology:
Molecular function: protein binding; small GTPase binding; phosphatidylinositol binding; ubiquitin binding
Biological process: Golgi to plasma membrane protein transport; protein localization to cell surface; Golgi to plasma membrane transport; intracellular protein transport; vesicle-mediated transport
Cellular component: clathrin-coated vesicle; early endosome membrane; Golgi apparatus; trans-Golgi network; endosome membrane
Genetic constraint (gnomAD): Loss-of-function variants: 19 observed, 27.47 expected, observed/expected ratio (o/e) 0.69, 90% interval 0.48 to 1.01. The upper end of that interval is the gene's LOEUF score, 1.01, which puts it in group 4 of 6, group 1 being the genes least tolerant of losing a copy. Missense variants: 321 observed, 325.96 expected, observed/expected ratio (o/e) 0.98, 90% interval 0.9 to 1.08. Synonymous variants: 141 observed, 131.3 expected, observed/expected ratio (o/e) 1.07, 90% interval 0.94 to 1.24.
Homologues: Orthologues: chimpanzee GGA2 (99% identical), macaque GGA2 (98% identical), dog GGA2 (92% identical), guinea pig GGA2 (91% identical), pig GGA2 (90% identical), rabbit GGA2 (87% identical), mouse Gga2 (85% identical), rat Gga2 (84% identical), Drosophila melanogaster Gga (26% identical), Drosophila melanogaster CG3529 (14% identical), Caenorhabditis elegans C07A12.7 (12% identical), Drosophila melanogaster Stam (11% identical), and 3 more. Paralogues in human: GGA1 (47% identical), GGA3 (46% identical), TOM1L2 (18% identical), TOM1 (17% identical), TOM1L1 (15% identical), HGS (14% identical), STAM (12% identical), STAM2 (12% identical), WDFY2 (10% identical), WDFY1 (10% identical).
Diseases named in the same sentence as GGA2 in open-access papers:
GGA2 is named in the same sentence as 18 diseases in open-access papers, as found by Europe PMC text mining. Sharing a sentence is not in itself a finding about the gene and the disease. The quoted sentences say what the papers report.
Alzheimer disease (2 papers, 2011 to 2014). A progressive, neurodegenerative disease characterized by loss of function and death of nerve cells in several areas of the brain leading to loss of cognitive function such as memory and language. "In addition, the GAT domains of human GGA1 and GGA3, but not GGA2, bind ubiquitin and ubiquitinated proteins, and GGA1 and GGA3, but not GGA2, are depleted in the brains of patients with Alzheimer disease." (PMID 24637350, 2014).
Ascites (1 paper, 2022). Accumulation of fluid in the peritoneal cavity (between the layers of the peritoneum that lines the abdomen). "Selection based on SNPs in the carboxypeptidase Q (CPQ, Gga2) and leucine rich repeat transmembrane neuronal 4 (LRRTM4, Gga22) gene regions resulted in a sex- and simulated altitude- dependent reduction of ascites incidence in two F2 cohorts of the MAS line." (PMID 35090566, 2022).
colorectal cancer (1 paper, 2018). A primary or metastatic malignant neoplasm that affects the colon or rectum. "Finally, GGA2 was upregulated in 30.8% of human hepatocellular carcinomas and 23.3% of colorectal cancers." (PMID 29358589, 2018). "Tissue arrays of HCC and colorectal carcinoma (CRC) were then examined by immunohistofluorescence microscopy using specific antibody against GGA2." (PMID 29358589, 2018).
endometrial cancer (1 paper, 2025). Primary or metastatic malignant neoplasm involving the endometrium (mucous membrane that lines the endometrial cavity).
glioblastoma (1 paper, 2017). The most malignant astrocytic tumor (WHO grade IV). "The GGA2-PRKCB fusion differs from the others examined in this study in that it has been found exclusively in low-grade glioma, which has a distinct mutational signature from high-grade glioblastoma." (PMID 28695888, 2017).
glioma (1 paper, 2017). A benign or malignant brain and spinal cord tumor that arises from glial cells (astrocytes, oligodendrocytes, ependymal cells). "While induction of the Bcan-Ntrk1 rearrangement readily resulted in high-grade gliomas, we never observed tumours after implantation of Fgfr3-Tacc3, Sec61g-Egfr or Gga2-Prkcb positive cell populations within the timeframe of analysis (150 days)." (PMID 28695888, 2017).
hepatocellular carcinoma (1 paper, 2018). A malignant tumor that arises from hepatocytes. "In subsequent studies, we investigated the relationship between GGA2 expression and cancer using hepatocellular carcinoma (HCC) tissues." (PMID 29358589, 2018).
Hypoglycemia (1 paper, 2012). A decreased concentration of glucose in the blood. "Furthermore, other than small size and perinatal hypoglycemia, the phenotypes were uninformative as to the basis for lethality of GGA2 mutant mice or GGA1/GGA3 double mutant mice." (PMID 23028818, 2012).
low grade glioma (1 paper, 2021). A grade I or grade II glioma arising from the central nervous system. "The 3' fusions TANC2-PRKCA, SLC44A1-PRKCA, and GGA2-PRKCB, found in lung squamous cell carcinoma (LUSC), papillary glioneuronal tumors (PGNT), and low-grade glioma (LGG), respectively, were selected for biochemical analysis." (PMID 33617877, 2021).
lung adenocarcinoma (1 paper, 2021). A carcinoma that arises from the lung and is characterized by the presence of malignant glandular epithelial cells. "GGA2 gene has been identified as a cooperative driver of EGFR-mediated lung adenocarcinoma, and GGA2 protein has been reported to be upregulated in HCC and CRC." (PMID 34799560, 2021). "Moreover, GGA2 reportedly maintains the cell surface expression of EGFR necessary for robust cell growth, and is recognized as a cooperative driver of EGFR-mediated lung adenocarcinoma, suggesting a new role of GGA2 in supporting cancer cell growth." (PMID 34799560, 2021).
lung carcinoma (1 paper, 2022). "Once again, SNP rs2285521 showed a significant correlation with decreased mRNA expression levels of GGA2 in lung cancer tissues, specifically in both additive (P = 4.85 × 10−3) and recessive (P = 8.29 × 10−3) models for LUSC, but not for LUAD." (PMID 35773316, 2022).
polydactyly (1 paper, 2016). A disease characterized by the presence of polydactyly, including syndromic and non-syndromic forms. "In addition, 16 SNPs that were also clustered on GGA2 may be significantly associated with polydactyly." (PMID 26859147, 2016).
prostate carcinoma (1 paper, 2026). A carcinoma that arises from epithelial cells of the prostate gland. "Functionally, GGA2 is instrumental in inhibiting oncogenic mechanisms by diminishing the proliferation, colony formation, invasion, and migratory capabilities of prostate cancer cells." (PMID 41898765, 2026).
tumor (7 papers, 2016 to 2026). "GGA2, FER and STXBP2: Exhibit varied expression patterns, with some showing significant differences between tumour and normal tissues." (PMID 41362116, 2025). "A B-cell associated signature distinguished HPV(+) from HPV(−) tumors, and included the DEGs CD200, GGA2, ADAM28, STAG3, SPIB, VCAM1, BCL2 and ICOSLG; the immune signal relative to T-cells was qualitatively similar between TILs of both tumor cohorts." (PMID 27462861, 2016). "Western blot analyses showed that the GGA2 expression was significantly higher (P < 0.05, Mann-Whitney U-test) in tumor regions than in non-tumor regions." (PMID 29358589, 2018). "The present study also suggests AP-1/GGA2 can support the expression of other RTKs, MET and ErbB4, which might have a significant impact on cancer growth in HCC, since MET is known to be overexpressed in this type of tumor." (PMID 34799560, 2021).
cancer (5 papers, 2018 to 2026). A tumor composed of atypical neoplastic, often pleomorphic cells that invade other tissues. "Thus, to establish the importance of AP-1/GGA2 in cancer progression the clathrin adapter-associated molecules, such as a small GTPase Arf1 that is necessary for membrane recruitment of AP-1, and several accessory proteins need to be investigated using human samples." (PMID 34799560, 2021). "Distinctly, GGA2 expression correlates with MSI and TMB across different cancers and is linked to the expression of immune checkpoint genes." (PMID 41898765, 2026). "The present results suggest that EGFR is stabilized in cancer cells that overexpress GGA2, likely supporting growth of HCC and CRC." (PMID 29358589, 2018). "Abnormal levels of GGA2 promoter methylation and genetic alterations may contribute to its dysregulated expression in some cancers." (PMID 41898765, 2026). "Preliminary studies indicate that the protein Golgi-associated, Gamma-adaptin Ear Containing, ARF Binding Protein 2 (GGA2) may influence various cancers." (PMID 41898765, 2026). "Our study shows that the oncogenic role of GGA2 in various cancers and GGA2 could be served as a biomarker of PARD." (PMID 41898765, 2026). "Therefore, accumulating evidence including our data suggests the importance of AP-1/GGA2 in cancer growth." (PMID 34799560, 2021). "Our findings suggest GGA2 could serve as a prognostic biomarker in various cancers." (PMID 41898765, 2026). "Collectively, these results suggest that AP-1 and GGA2 function in recycling endosomes to retrieve endocytosed EGFR, thereby sustaining its cell surface expression and, consequently, cancer cell growth." (PMID 34799560, 2021). "Depletion of AP-1 or GGA2 also reduced cell contents of other tyrosine kinases, MET and ErbB4, and therefore, suppressed the growth of H1975 cancer cells in culture and xenograft model." (PMID 34799560, 2021). "Together with recent findings that the depletion of GGA2 suppresses cell proliferation in ARPE-19, and two NSCLC-derived cancer cell lines, PC9 and H1975, it is most likely that both AP-1 and GGA2 have a fundamental influence on cell growth by sustaining the expression of EGFR." (PMID 34799560, 2021).
GGA2 also shares sentences with these, for which no sentence is quoted: infection (1 paper); lung squamous cell carcinoma (1); papillary glioneuronal tumor (1).